INS (insulin)
Diseases named in the same sentence as INS in open-access papers (continued):
Sharing a sentence is not in itself a finding about the gene and the disease.
memory impairment (71 papers, 2014 to 2026). "Impaired insulin signaling in the hippocampus has been associated with spatial learning and memory impairments, likely due to a downregulation of synaptic transmission." (PMID 35557971, 2022). "For example, the i.c.v-injection of LPS caused memory impairments and desensitized insulin-signaling in the hippocampus of rats, as implied by Ser307-phosphorylated IRS-1 and decreased phospho-Akt levels, whereas insulin co-treatment rescued the latter." (PMID 36117625, 2022). "Recent studies have identified the key mechanisms by which the brain becomes resistant to insulin in AD and how impaired insulin signaling in AD is linked to memory impairment." (PMID 34489627, 2021). "The current study aimed at investigating the possible effects of insulin against scopolamine-induced memory impairment in Wistar rat and its underlying molecular mechanisms." (PMID 31031891, 2019). "Many studies have reported that memory impairment triggered by diets is associated to specific insulin resistance." (PMID 30515083, 2018). "The ICV-STZ rats develop insulin resistant brains state associated with sAD like neuropathological changes and memory impairment." (PMID 29163130, 2017). "This accumulation of Aβ and associated memory impairments was reversed with the acute administration of insulin." (PMID 26693205, 2015). "The insulin signaling pathway has been linked to aging and cognitive function, and a dysfunctional signaling system may be associated with memory impairment." (PMID 40589410, 2025). "In addition, FF better protected against memory impairment than CS by reducing amyloid-β deposition more than CS and did so in association with potentiating hippocampal insulin signalling and reducing neuroinflammation." (PMID 35076339, 2022). "In addition, the attenuation of insulin signaling in the hippocampus is associated with memory impairment." (PMID 30380669, 2018). "Intranasal insulin administration with intranasal regular insulin at 40 IU daily for 4 months improved memory impairment and verbal memory in MCI and AD and, importantly, improved performance in patients with early AD." (PMID 40943177, 2025). "The results demonstrate that SchA treatment improves insulin sensitivity, reduces blood glucose, and significantly reduces memory impairment." (PMID 40589410, 2025). "We investigated the effects of treadmill exercise and intranasal insulin on learning and memory impairment and the expression of IGF1, BDNF, and GLUT4 in hypothalamus." (PMID 38987609, 2024). "Metabolic side effects, such as abnormal glucose metabolism and lower insulin sensitivity, are well-established consequences of circadian rhythm disruption, as are memory impairments." (PMID 39147588, 2024). "Although the mechanism has not been clarified, many studies in recent years have shown the ameliorative effect of intranasal insulin on memory impairment in animal models and clinical studies, respectively." (PMID 36430894, 2022). "Taken together, these studies suggested that intranasal insulin had a beneficial effect on memory impairment." (PMID 36430894, 2022). "In recent years, many studies have shown that intranasal insulin significantly ameliorates memory impairment in animals in various disease models." (PMID 36430894, 2022). "In particular, acetate has been reported to increase insulin resistance and act as a proinflammatory factor to exacerbate memory impairment." (PMID 35892598, 2022). "Animal models showed that the gene expression of IRs in the hippocampus was upregulated after spatial learning, and the ameliorative effect of intranasal insulin on memory impairment was also affected by the levels of IRs." (PMID 36430894, 2022). "Other studies have shown that even systemic administration of exogenous insulin can contribute to the onset of memory impairment and neuronal dysfunction." (PMID 34068096, 2021).
memory impairment (continued). "Intranasal insulin has also been investigated as a potential protective treatment against further cognitive decline in those with memory impairments." (PMID 34867762, 2021). "This indicates that intranasal insulin prior to anesthesia protects against anesthesia-induced memory impairment in adulthood." (PMID 34326413, 2021). "This study aimed to investigate the molecular mechanism of berberine in relieving inflammatory effects and modulating the cholinergic and insulin signaling pathways to improve spatial learning and memory impairment in DM rats." (PMID 31551793, 2019). "The positive effects of insulin in learning were first shown in 1976 when insulin administration attenuated memory impairment in rats subjected to hippocampal lesions." (PMID 31231176, 2019). "Collectively, current data showed that berberine alleviates the inflammatory, cholinergic and insulin signaling deficits in diabetic hippocampal tissue, and exhibits a protective effect on spatial learning and memory impairment." (PMID 31551793, 2019). "Overall, these hormonal changes support the link of memory impairment, peripheral dysmetabolism and central insulin resistance." (PMID 31471539, 2019). "HFD rats demonstrated abnormal insulin signaling and tau hyperphosphorylation in the cerebral cortex, as well as memory impairments that suggested reduced cerebral function." (PMID 29673239, 2018). "Disruption of insulin signaling reduces the level of acetyl-CoA, a precursor of acetylcholine, leading to reduced synthesis of acetylcholine and memory impairment." (PMID 28832656, 2017). "Future studies are needed to investigate the application of insulin/IGF-1 as it may normalize alcohol-related memory impairments, particularly in males." (PMID 41400881, 2025). "Deoxyschizandrin, schisantherin A, schisandrin A and C, and schisanhenol have been shown to alleviate memory impairment by inhibiting the production of inflammatory cytokines and lipid peroxides and improving insulin sensitivity in several animal models with memory deficits." (PMID 39519586, 2024). "Memory impairment, Aβ aggregation, tau hyper-phosphorylation, neuroinflammation, dysregulation of insulin signaling, and the downregulation of miR-26a, miR-124, miR-29a, miR-181b, miR-125b, miR-132, and miR-146a are observed in the hippocampus of rats exposed to Aβ oligomers." (PMID 38338859, 2024). "Disordered brain insulin signaling also plays a role in learning and memory impairment." (PMID 36713033, 2023). "Magnetic resonance spectroscopy analysis of neuronal-derived extracellular vesicles found that neuronal insulin signaling abnormalities were already present in the first episode of SCZ, and were linked to memory impairment and lower brain glucose utilization in the occipital cortex." (PMID 36082534, 2022). "In addition, this study has investigated the effect of resveratrol on hippocampal miRNA-21 expression and brain insulin signaling as a promising treatment for memory impairments and cognitive dysfunction in diabetic rats." (PMID 35781592, 2022). "In other clinical studies, positive results demonstrated that intranasal insulin improves memory impairments in AD and in mild cognitive memory patients; the authors also note that the APOE ε4 allele does not appear to have any effect on insulin treatment efficacy." (PMID 34576151, 2021). "Training-induced lipid levels and insulin sensitivity amelioration may improve memory impairment in diabetic rats." (PMID 34837961, 2021). "Could insulin and PPARγ agonists be used to ameliorate psychostimulant withdrawal-induced memory impairment?" (PMID 31396113, 2019). "This could be one of the possible reasons for a need of higher dose range of CDRI-08 in correcting the memory impairments along with its antidiabetic effects by increasing the targeting function of the insulin in glucose metabolism." (PMID 26161865, 2015).
memory impairment (continued). "Therefore, lipoic acid could be considered a promising natural and nutritional intervention to prevent western diet-induced central nervous system insulin resistance and memory impairment." (PMID 28710347, 2017). "Transfection with miR-200b/miR-200c alleviated memory impairment and improved spatial learning through regulation of S6K1-mediated insulin signaling." (PMID 33790780, 2021). "Insulin, or glucagon-like peptide 1 (GLP-1) receptor agonists inhibited Aβ induced phosphorylation eIF2α, indicating that stimulating insulin signalling may prevent inflammation mediated synaptic loss and memory impairment through inhibiting/downregulating the PKR signalling pathway." (PMID 26693205, 2015). "Further investigation will be required to delineate the long-term efficacy, mechanistic basis, responder characteristics and safety of insulin detemir with a larger sample size, particularly for individuals with memory impairment and APOE ε4 negative." (PMID 38441832, 2024). "This does not align with several study findings that intranasal insulin administration improves memory in both healthy controls and patients with memory impairments." (PMID 37234022, 2023). "Although mechanistic studies have been insufficiently conducted, adequate animal studies have demonstrated a significant improvement in memory impairment with insulin; however, this improvement has not been as evident in clinical studies." (PMID 36430894, 2022). "Additionally, insulin’s effects on the Ca2+-dependent hippocampal after hyperpolarization (AHP), a neurophysiological marker that increases in aging animals with memory impairment, were investigated." (PMID 34068096, 2021). "Aged mice displayed memory impairments without an increase in blood glucose and plasma insulin levels, despite an increase in body weight." (PMID 31426549, 2019). "The insulin signal pathway of the brain in patients with AD was impaired and the activity of GSK-3β was significantly increased; the activation of GSK-3β in the hippocampus led to phosphorylation of Tau proteins in the T2DM rodent, which further affected memory impairment." (PMID 34867302, 2021). "Elevated concentrations of plasma glucose appear to play a role in memory impairment, and it has been suggested that insulin might also have a negative effect on cognitive function." (PMID 25798199, 2015). "As DOX does not appear to affect insulin sensitivity, MET likely has little effect on improving glucose-mediated memory impairment, which is supported by our findings." (PMID 32156040, 2020).
acute pancreatitis (69 papers, 2011 to 2025). An acute inflammatory process that leads to necrosis of the pancreatic parenchyma. "After adjustments for propensity score, insulin and use of medication potentially associated with acute pancreatitis, the odds ratio with exenatide twice daily exposure was 0.95 (95%CI 0.65–1.38)." (PMID 22416857, 2012). "In cases refractory to insulin, particularly when end-organ damage is evident or there is a high risk of acute pancreatitis or multiorgan failure, rescue therapy with therapeutic plasma exchange (TPE) may be required." (PMID 41393592, 2025). "Hence, research is needed to confirm whether insulin resistance after acute pancreatitis is caused by AP." (PMID 36979645, 2023). "This study also provides the first evidence that exogenous therapeutic administration of insulin with tight moment-to-moment glucose control, using the hyperinsulinaemic euglycaemic clamp reduces early pancreatic injury (plasma amylase) associated with acute pancreatitis (AP)." (PMID 34282152, 2021). "Due to repeated episodes of acute pancreatitis, the scarring of pancreas parenchyma takes place, affecting insulin production capacity, leading to the development of insulin resistance." (PMID 39941188, 2025). "Acute pancreatitis induces a hypermetabolic state (involving a reduction in body mass, insulin resistance, protein catabolism, and lipolysis), which is exacerbated by inadequate nutrition and infections." (PMID 39941188, 2025). "Dog C remained clinically controlled with the addition of intermittent mealtime bolus insulin (porcine Lente) for 5 months until she was euthanized after being hospitalized with acute pancreatitis at the referring veterinarian's office." (PMID 35621084, 2022). "The results showed that SGLT-2i combined with DPP-4i, GLP-1RA, metformin, insulin, glinide, ACEI and PPI showed an increased risk of acute pancreatitis (adjusted OR 1.39, 1.97, 1.29, 1.21, 2.55, 1.34, and 1.32, respectively)." (PMID 36467046, 2022). "The current study shows that CL treatment can improve blood glucose homeostasis and insulin sensitivity in obese mice, and attenuate lung injury in rats with severe acute pancreatitis." (PMID 35280997, 2022). "Melatonin was reported to regulate insulin secretion and has a protective effect on endoplasmic reticulum stress in an experimental acute pancreatitis model." (PMID 34247466, 2021). "This was achieved by combining caerulein infusion-induced acute pancreatitis with continuous insulin infusion with tight moment-to-moment glycaemic control using the hyperinsulinaemic euglycaemic clamp." (PMID 34282152, 2021). "The current study provides the first direct evidence that endogenously released insulin directly protects pancreatic acinar cell injury during two mechanistically distinct experimental models of acute pancreatitis (caerulein and POA/ethanol-induced)." (PMID 34282152, 2021). "Collectively, these data suggest that endogenous insulin directly protects pancreatic acinar cells during experimental models of acute pancreatitis." (PMID 34282152, 2021). "In animal models of acute pancreatitis, insulin-treated pancreatic acinar cells are protected against cytosolic calcium overload and cellular death." (PMID 33665687, 2021). "Fibroblast growth factor 21 (FGF21), a metabolic hormone with pleiotropic effects on glucose and lipid metabolism and insulin sensitivity, alleviates the process of acute pancreatitis (AP)." (PMID 32233059, 2020). "In streptozotocin (STZ)-induced diabetic mice, in which insulin secretion is impaired, caerulein-induced acute pancreatitis is much worse than in control mice." (PMID 24993827, 2014). "The current study explored the effects of intensive insulin therapy (IIT) combined with low molecular weight heparin (LMWH) anticoagulant therapy on severe acute pancreatitis (SAP)." (PMID 24944612, 2014).
acute pancreatitis (continued). "We report the case of a 10-year-old girl with clinical acute pancreatitis and diabetic ketoacidosis debut, along with incidental finding of an SH, who had a good outcome after treatment with insulin intravenous infusion." (PMID 24804116, 2011). "In addition, a shift of magnesium from the extracellular to the intracellular compartment can contribute to decreased serum levels in certain clinical conditions, such as refeeding syndrome, acute pancreatitis, or insulin therapy, but is quite infrequent." (PMID 41473199, 2025). "Although insulin is widely used for early lipid lowering in hypertriglyceridemic acute pancreatitis, the clinical benefit of heparin combined with insulin remains unclear." (PMID 41201803, 2025). "This randomized clinical trial of adults with acute pancreatitis assesses whether low-molecular-weight heparin combined with insulin is superior to insulin alone in reducing new-onset organ failure and/or mortality." (PMID 41201803, 2025). "A cohort study of patients with acute pancreatitis from New Zealand had shown that the use of insulin during or after the treatment of acute pancreatitis, had increased the risk of developing recurrent acute pancreatitis and chronic pancreatitis by 70% over a mean follow-up period of seven years." (PMID 37337255, 2023). "Both insulin and plasma exchange (PE) are used in hypertriglyceridemic acute pancreatitis (HTG-AP)." (PMID 35492338, 2022). "After adjustment for potential confounders, the risk of acute pancreatitis of SGLT-2i combined with DPP-4i, GLP-1RA, metformin, insulin, glinide, ACEIs and PPIs was higher than that of SGLT-2i monotherapy (adjusted OR 1.39, 1.97, 1.29, 1.21, 2.55, 1.34, 1.32, respectively)." (PMID 36467046, 2022). "Given the protective effect of endogenous insulin during acute pancreatitis—which was abolished in diabetic Ins2Akita mice that lack insulin secretion and PACIRKO mice that lack acinar insulin receptors—we next wanted to assess the potential protective effects of exogenously administered insulin." (PMID 34282152, 2021). "Furthermore, in a large scale population-based study the incidence of acute pancreatitis was markedly reduced among insulin-treated diabetic patients." (PMID 24993827, 2014). "This therefore suggests that insulin therapy with tight glycemic control, for example using the hyperinsulinaemic-euglycemic clamp, might be an effective treatment for severe acute pancreatitis." (PMID 24993827, 2014). "Also, insulin signaling in acinar cells protects them from Ca2+ overload during acute pancreatitis." (PMID 39720531, 2024). "The increased risk of acute pancreatitis associated with the use of SGLT-2i in combination with insulin is not known and may be related to the patient’s own disease." (PMID 36467046, 2022). "Thus, we anticipate that low level of serotonin in patients with acute pancreatitis could possibly result in disruption of the synthesis of insulin, which resulted in a pathological high and sustained glucose concentration." (PMID 34772352, 2021). "Such drugs might have a more specific protective effects without some of the more adverse systemic effects, technical difficulties or safety issues of insulin administration that could be used to treat all forms of acute pancreatitis from mild to severe disease." (PMID 34282152, 2021). "In this multicenter randomized clinical trial of 533 adults with acute pancreatitis, low-molecular-weight heparin with insulin was not superior to insulin alone in reducing new-onset organ failure and/or mortality." (PMID 41201803, 2025). "Therefore, a controlled trial evaluating the efficacy of intravenous insulin, heparin, and TPE may helpful for determining the best choice for the treatment of acute pancreatitis secondary to HTG." (PMID 31203594, 2019).
acute pancreatitis (continued). "In conclusion, insulin therapy for HTG in the third trimester of pregnancy could increase the pregnancy weight gain compliance rate, decrease blood lipid levels and the incidence of severe complications such as HTG acute pancreatitis (HTG-AP), and improve pregnancy outcomes." (PMID 36405614, 2022). "Both intravenous insulin and plasmapheresis are not generally recommended for HTG-induced acute pancreatitis." (PMID 41378317, 2025).